IL1B (interleukin 1 beta)
Diseases named in the same sentence as IL1B in open-access papers (continued):
Sharing a sentence is not in itself a finding about the gene and the disease.
autoimmune disease (continued). "Although the mechanism of IL-1β production has been discovered in infectious and autoimmune diseases, its production mechanism in the tumor microenvironment is unclear." (PMID 30586442, 2018). "In autoimmune diseases such as RA and multiple sclerosis (MS), IL-17 is produced by helper T (Th) cells that are stimulated by IL-1β and IL-6 derived from phagocytes such as macrophages and from tissue cells." (PMID 28316374, 2017). "Over the past decade, the concept of targeting cytokines to treat autoimmune diseases has evolved at a rapid pace, such as some medicines approved by the drug administration to target IL-1β, IL-5, IL-6, IL-2, TNF-α, and IFN-γ." (PMID 29250557, 2017). "Th17 cells differentiate in response to IL-1β, IL-6, IL-23, and TNF-α; secrete IL-17A, IL-17F, and IL-21; and play a critical pathogenic role in T cell-mediated autoimmune diseases." (PMID 28458638, 2017). "IL-1β is involved in inflammatory responses and elevated levels have been found in some autoimmune diseases." (PMID 28286780, 2017). "Dysregulation of both IL-1β and its related pathways is involved in inflammatory/autoimmune disorders and in a wide range of other diseases." (PMID 28331244, 2017). "It is possible that IL-1β also induces Tcon cell resistance to suppression in autoimmune disease settings, but this remains to be investigated." (PMID 27242798, 2016). "For example, IL1B, a gene target of multiple drugs targeting different autoimmune diseases, is a signature disease gene for COPD." (PMID 27089880, 2016). "Recent progress indicates that inflammasome activation and IL-1β production are involved in various inflammatory and autoimmune diseases, including liver diseases." (PMID 27942420, 2016). "The blockade of IL-1 activity (especially IL-1β) is a standard therapy for patients with autoimmune diseases." (PMID 27809221, 2016). "IL-1β is regarded as a potent proinflammatory cytokine that is involved in many autoimmune diseases in humans." (PMID 26713004, 2015). "Blockage of TNF-α is already used as standard treatment in various autoimmune diseases, whereas clinical trials to evaluate blockage of IL-6 and IL-1β in inflammatory diseases and cancer are ongoing." (PMID 23616009, 2013). "This is consistent with studies which show that systemic blockade of IL-1β activity using IL-1RA abrogates symptoms in autoimmune diseases despite undetectable levels of systemic IL-1β." (PMID 23840908, 2013). "Microglial IL-17 is produced in response to IL-23 and IL-1β, and contributes to autoimmune diseases in the CNS." (PMID 22361049, 2012). "Owing to their central role in the secretion of active IL-1β, inflammasomes play an important role in the control of the immune response to tumors and infections, and also in autoimmune diseases such as MS." (PMID 22768094, 2012). "CD8α− DCs from GM-CSF treated mice that produce significantly lower levels of pro-inflammatory cytokines IL-12 and IL-1β compared to the DCs from control mice can induce and/or expand Foxp3+ Tregs and suppress autoimmune diseases." (PMID 21779356, 2011). "In fact, many autoimmune diseases, such as rheumatoid arthritis, are associated with increases in TNF-α and IL-1β levels, and treatments that block these cytokines have proven beneficial in animal models and clinical settings." (PMID 15550215, 2004). "Furthermore, when comparing with other autoimmune diseases, we found that the reduction of pro-inflammatory cytokines, including TNF-α, IL-1α, and IL-1β, is associated with decreases disease occurrence." (PMID 40206211, 2025). "highlighted the significance of IL-1β-mediated IL-8 expression in autoimmune disease pathogenesis." (PMID 40406113, 2025). "ATG16L1 is crucial in regulating inflammatory responses and autoimmune diseases by suppressing IL-1β signaling, and its inhibition by EHEC may trigger host inflammatory reactions." (PMID 41522448, 2025).
autoimmune disease (continued). "Overall, TNF-α, IL-1β, and IL-6 could be valid molecular targets in light of their deregulation in autoimmune diseases and their involvement as activators of transduction cascades involving ADAM17." (PMID 39768182, 2024). "Similarly, the levels of Arg-1 and IL-1β were positively correlated with the percentage of MDSCs and Th17-mediated autoimmune diseases." (PMID 37733169, 2024). "Anakinra (Kineret, Swedish Orphan Biovitrum AB, Stockholm, Sweden) is a recombinant form of the IL-1R antagonist that inhibits the activity of IL-1β and has been primarily used as a treatment for autoimmune diseases that involve dysregulated IL-1 signalling, such as rheumatoid arthritis." (PMID 39184952, 2024). "IL-1β and IL-8 all belong to cells Factors can regulate the body’s immune response through receptors and play an important role in mediating trauma, infection, autoimmune diseases, and inflammatory reactions." (PMID 39534507, 2024). "IL-1β plays a key role in proinflammatory responses, providing resistance to microbial infections, as well as being involved in numerous inflammatory and autoimmune diseases and cancers." (PMID 37833877, 2023). "Reductions in cytokines like IL-1β, IL-6, IL-12, and IL-17 caused by BTK inhibitiors in some primary autoimmune diseases may suggests possible mechanism to abrogate iRAEs." (PMID 37081866, 2023). "In this study, we found that metformin pretreatment significantly reduced the mRNA levels of cytokines stimulated by IL-1β and reduced inflammation at the protein level; these results are similar to previous findings in uveitis, other autoimmune diseases, and TAO." (PMID 36555150, 2022). "IL-1β plays a vital role in autoimmune disease as an important pro-inflammatory cytokine." (PMID 36088289, 2022). "Interactions between type I IFN and IL-1β pathways may play an important role not only during pathogen-induced inflammation, but also in the regulation of the pathomechanisms of various autoimmune diseases." (PMID 36293012, 2022). "A study found that rapamycin decreased macrophage secretion of IL-18 and IL-1β by reducing caspase-1 activation, indicating that inhibition of mTOR may be advantageous for patients with inherited autoimmune diseases." (PMID 36595872, 2022). "Collectively, the effect of NLRP3 inflammasome in autoimmune diseases involves the following two aspects: due to caspase-1 being the effector of inflammasome structure, IL-1β, IL-18, and pyroptosis modulated by activated caspase-1 play a major role in autoimmune diseases." (PMID 34707607, 2021). "The overproduction of IL-1β is harmful and can trigger autoimmune diseases." (PMID 34941743, 2021). "The risk of bone loss and fracture is increased in individuals with RA and other autoimmune diseases because OCs, mediated by inflammatory factors, such as TNFα and IL-1β, induce not only erosion of cartilage and bone locally in affected joints, but also degradation of bone systemically." (PMID 35011694, 2021). "Excessive production of IL-1β is related to inflammatory and autoimmune diseases." (PMID 34122073, 2021). "Because the NLRP3 inflammasome may trigger the release of IL-1β after stimulation with various danger signals, it represents a potentially effective target to regulate the onset and development of various autoimmune diseases, such as T1DM." (PMID 32973739, 2020). "Moreover, ADT has been revealed to reduce Th1 and Th17 responses and also the concentration of inflammatory cytokines involved in several autoimmune diseases, including IL-1β, IL-2, tumor necrosis factor (TNF)-α and interferon (IFN)-γ." (PMID 32580478, 2020). "Therefore, reducing the level of IL-1β secretion is an effective treatment for such autoimmune diseases." (PMID 32595732, 2020). "Because microglia also produce IL-1β and IL-17, these cytokines may act in an paracrine manner to induce IL-17 expression in astrocytes, and thereby contribute to autoimmune diseases." (PMID 33081798, 2020).
autoimmune disease (continued). "Taken together, our data indicate the importance of the non-transcriptional/translational activity of canonical NF-κB in the activation of ERK1/2 signaling involved in the IL-1β-induced development of autoimmune diseases affecting the synovial tissue, such as RA." (PMID 33117381, 2020). "The recognition of the importance of IL-1β in the pathogenesis of different disorders already resulted in the development of diverse therapeutic strategies inhibiting the IL-1 system mainly for the treatment of diverse autoimmune diseases." (PMID 31019507, 2019). "Depending on the particular autoimmune disease and stage of development, type I IFNs can promote disease through chemokine expression and antigen presentation or protect against damage through regulation of proinflammatory cytokines, including IL-1β and TNF-α." (PMID 29559569, 2018). "Although the IL-1β (rs16944) polymorphism was reported to be associated with the risk of many autoimmune diseases, our data indicated that it did not influence susceptibility to ITP." (PMID 30140708, 2018). "Moreover, it is a well-known fact that inflammasome activation can produce mature IL-1β in various pathological environments, such as infectious and autoimmune diseases." (PMID 30586442, 2018). "As our data demonstrated that BVDU could inhibit IL-6, IL-12, IL-23 and IL-1β production, which participate in many other autoimmune diseases such as type 1 diabetes, we further analyzed the therapeutic effect of BVDU on STZ-induced type 1 diabetes." (PMID 28272439, 2017). "IL1B plays a key role in the pathogenesis of inflammatory and autoimmune diseases." (PMID 27749914, 2016). "Furthermore, we had previously shown that IL-1β, induced via caspase-1 and Nlrp3, plays a critical role in IL-17-mediated pathology in autoimmune disease." (PMID 23592988, 2013). "Moreover, IL-1β promotes the differentiation of naive T cells into Th17 cells, a subset of T cells that plays a role in autoimmune diseases and defense against extracellular pathogens and contributes to the activation and differentiation of B cells in the process of antibody production." (PMID 39859545, 2025). "Our findings highlight the critical role of IL-1β in follicular T cell activation and suggest that targeting IL-1β signaling in Tfh and Tfr cells could be a promising strategy for treating antibody-mediated autoimmune diseases." (PMID 40392614, 2025). "It was shown that rCpstefin had a potential modulatory effect on macrophage inflammation, which suggested that rCpstefin could be further applied to the study of autoimmune diseases characterized by a significant increase in IL-1β, IL-6, and TNF-α, such as inflammatory bowel inflammation." (PMID 38792680, 2024). "Autophagy may regulate the IL-1β and IL-23 secretion to protect from autoimmune diseases." (PMID 36941573, 2023). "In addition, increased caspase-1 activation and IL-1β production by the constitutively active autoimmune disease-associated variants of NLRP3 were also linked to autoimmune diseases, indicating a crucial need for appropriate NLRP3 activation and IL-1β production." (PMID 35246034, 2022). "Previous studies have shown that both CD14+ and CD14dim monocytes can produce cytokines TNF‐α, IL‐1β, and type I interferon under various conditions such as infection, inflammatory and autoimmune diseases, and cytokine‐release syndrome, though different signaling pathways may be involved." (PMID 35347900, 2022). "IL-1β is an effective activator of dendritic cell subsets and a regulator of T-cell differentiation and function; in contrast, IL-10 is the most crucial cytokine to inhibit the proinflammatory response and limit the overimmune response of various autoimmune diseases." (PMID 35302166, 2022). "However, if IL-1β is overactivated, chronic oxidative stress, oxidative damage of DNA sequence, epigenetic changes, and autoimmune diseases may occur." (PMID 34853599, 2021).
autoimmune disease (continued). "Further studies are needed to investigate the unknown mechanisms through which programmed cell death modalities are involved in the production of pro-inflammatory mediators (e.g., IL-1β), and the amplification of chronic tissue inflammation in autoimmune diseases." (PMID 34548542, 2021). "Similarly, dysregulated IL-1β expression contributes to autoimmune diseases and cancer." (PMID 33776573, 2021). "Since our data demonstrated that BVDU could inhibit IL-6, IL-12, IL-23 and IL-1β production in DCs, and these pro-inflammation cytokines played a critical role in initiating the autoimmune disease, we hypothesized that this drug might have promising potential in treating autoimmune disease." (PMID 28272439, 2017). "Importantly, FK506 may suppress the function of T cells via calcineurin inhibition and may also directly suppress the production of a variety of T-cell-triggered cytokines such as IFN-γ, IL-17, TNF-α and IL-1β in several autoimmune diseases." (PMID 27501378, 2016). "However, given the extensive effects of IL-1β on adaptive immune cells, autophagy might also affect the outcome of autoimmune diseases by modulating IL-1β production." (PMID 23596443, 2013). "Therefore, the newly discovered potent inhibitory action of NPs/NPR1-axis on IL-1β secretion in DCs suggest that the targeting of NPs/NPR1 axis could be a promising therapeutic approach for controlling excessive inflammation in autoimmune diseases and chronic inflammatory conditions." (PMID 40643749, 2025). "M1 macrophages are prevalent in the pro-inflammatory environment of autoimmune diseases such as Systemic Lupus Erythematosus (SLE), and thus produce cytokines such as IL-1β, interferon (IFN-γ), and IL-6." (PMID 39329752, 2024). "In the mechanisms studies based on iPSCs, it is demonstrated that the pro-inflammatory cytokines such as TNF-α, IL-1β, and IFN-γ are the cores for driving disease progression in autoimmune diseases." (PMID 38720903, 2024). "IL-1β, IL-8 and TNF-α are the major pro-inflammatory factors, which play significant roles in the development of inflammatory and autoimmune diseases." (PMID 37791345, 2023). "A similar reduction in IL-1β is also observed with VPA in animal models of injury and autoimmune diseases." (PMID 36412793, 2022). "In summary, the IL-1β-ERK-RORγtS182 circuit protects against T cell-mediated inflammation and provides potential therapeutic targets to combat autoimmune diseases." (PMID 35294872, 2022). "In response to ‘second necrosis’, a mass of pro‐inflammatory factors including TNF‐α, IL‐1β and IFN‐γ can be released that subsequently induce inflammation or lead to the development of autoimmune disease." (PMID 33686740, 2021). "Our patients demonstrated elevations of five biomarkers of inflammation (IL-1β, IL-21, TNFα, INFγ, and CD30) that are known to be elevated in autoimmune disorders such as RA and SLE." (PMID 33562074, 2021). "Proinflammatory cytokines such as IL-1β, IL-6, and TNF-α, which play crucial roles in the development of inflammatory diseases, are also involved in the innate immunity and autoimmune diseases." (PMID 34824594, 2021). "Microarray analysis of B cells has revealed that high ANA HIV+ subjects had upregulation of IL1B and IL23 genes, which favor immune activation and are essential for disease development in several models of autoimmune disease." (PMID 30764863, 2019). "In addition, IL-1β initiates innate immunity through binding with the IL-1 receptors and has been further proved to be essential in the pathogenesis and progression of autoimmune disease, including experimental autoimmune encephalomyelitis, systemic lupus erythematous and ITP." (PMID 29499727, 2018). "Th17 cells, a key player in autoimmune diseases and antibiosis, are differentiated from naïve T cells (CD4+) stimulated by IL-6, TGF-β, IL-1β, IL-21 and IL-23 and release IL-17A, IL-17F, IL-21 and IL-22." (PMID 28899359, 2017).
autoimmune disease (continued). "MIF is a pro-inflammatory mediator and an upstream regulator of expression of many cytokines, including IL-1b, IL-8, IFN-ɤ, TNF-α, and IL-6 in autoimmune diseases." (PMID 25506398, 2014). "A broad range of infectious and autoimmune diseases that involve IL-1β have been associated with inappropriate activation of the inflammasome, while in several other disease models in which IL-1β plays a crucial role, the inflammasome appears not to be involved." (PMID 26266796, 2013). "NF-κB, a nuclear transcription factor, regulates the expression of various genes, including IL-1β, i-NOS, and COX-2 that play critical roles in apoptosis and autoimmune diseases." (PMID 20107539, 2009). "It has been reported that in autoimmune diseases, the formation of an inflammatory microenvironment induces the production of CCL2 in response to inflammatory cytokines such as IL‐1β, which recruits and expands macrophage aggregation at the site of inflammation." (PMID 40500868, 2025). "In autoimmune diseases, the Slc7a5-mTORC1 pathway may offer a new therapeutic approach, LAT1 deletion or inhibition effectively regulates IL-23 and IL-1β-induced PI3K/AKT/mTOR activation." (PMID 41385507, 2025). "In a model of passive experimental autoimmune encephalomyelitis, IL-1β-, TNFR-, and Fas-deficient recipients all failed to develop diseases, suggesting that memory CD4+ T cell–induced IL-1β is a critical driver of autoimmune disease pathology." (PMID 40279312, 2025). "However, in a proinflammatory environment, as observed in a mouse model of autoimmune disease, primary biliary cholangitis, Man impairs the production of TNF‐α, IL‐1β, Arg1, and IL‐6 cytokines." (PMID 39950558, 2025). "Anakinra inhibits the activity of IL-1β, but the results from other autoimmune diseases have not been extrapolated to IBD." (PMID 40002819, 2025). "IL-1β, an identified hub gene in CCS, is a classical target in autoimmune diseases." (PMID 38297356, 2024). "In this study, a cross-sectional analysis of multiple autoimmune disorders revealed that the expression of IFN-signature genes was high in autoimmune diseases such as SLE, and that IL-18 or IL-1β signature was high in autoinflammatory diseases such as Behcet’s disease." (PMID 35686127, 2022). "Cytokines and chemokines that we found elevated in POTS patients, in contrast to our non-POTS group, and that have been related to autoimmune diseases, include not only IL-21, but also IL-1β, INFΥ, CD30, and IL-17." (PMID 35269395, 2022). "The toxic targets of LGT were mainly distributed in the downstream of the pathways, such as LCN2, IL6, IL1B, and CSF3, and ultimately target the inflammatory host defense autoimmunity, proinflammatory activities and other inflammatory reactions and autoimmune diseases." (PMID 36339610, 2022). "Moreover, several previous studies have illustrated that activated NF-κB regulates the expression of genes such as IL-1β, IL-6, and TNF-α and promotes the occurrence, development and pathogenesis of autoimmune diseases, chronic infections and cancer." (PMID 34017253, 2021). "Furthermore, disruption of Rubicon leads to upregulation of IL‐1β, IL6 and TNF‐α secretion, and the mice fail to gain weight and develop an autoimmune disease that resembles systemic lupus erythematosus." (PMID 33586810, 2021). "Recent studies have shown that pyroptosis is a characteristic of autoinflammatory and autoimmune diseases; We found pyroptotic phenomena reflected as high expression of NLRP3, caspase-1, GSDMD, and IL-1β in endometrial cancer lesions as identified by IHC analyses." (PMID 31924176, 2020). "In autoimmune disease, dendritic cells play an indisputable role in instructing the polarization of CD4+ Th17 cells in immune response through generation of cytokines such as IL-6, IL-23, and IL-1β." (PMID 33643041, 2020).